MGAT3 (beta-1,4-mannosyl-glycoprotein 4-beta-N-acetylglucosaminyltransferase)
Diseases named in the same sentence as MGAT3 in open-access papers (continued):
Sharing a sentence is not in itself a finding about the gene and the disease.
MGAT3 also shares sentences with these, for which no sentence is quoted: glioma (3 papers); bladder cancer (2); colon carcinoma (2); leukemia (2); type 1 diabetes (2); acute myeloid leukemia (1); autoimmune disease (1); cardiac arrest (1); chronic hepatitis (1); conduct disorder (1); congenital disorder of glycosylation (1); endometrioid ovarian cancer (1); gynecological cancer (1); hematological malignancies (1); inflammatory bowel disease (1); intestinal polyp (1); liver diseases (1); metastatic colorectal cancer (1); metastatic melanoma (1); multiple myeloma (1); multiple sclerosis (1); myelodysplastic syndrome (1); neurodegenerative disease (1); non-Hodgkin lymphoma (1); Obesity (1); ovarian adenocarcinoma (1); pancreatitis (1); primary biliary cirrhosis (1); Type 2 diabetes (1); viral infection (1).